ARL5A (ARF like GTPase 5A)
Description:
Lacks ADP-ribosylation enhancing activity.
Synonyms: ARFLP5; ARL5
Tractability: Small molecule: a structure with a bound ligand is known.
Gene: Protein-coding gene on chromosome 2 (151,788,984 to 151,828,531, reverse strand). Ensembl gene ENSG00000162980.
Gene Ontology:
Molecular function: GTP binding; GTPase activity
Biological process: protein localization to Golgi membrane; intracellular protein transport
Cellular component: trans-Golgi network
Genetic constraint (gnomAD): Loss-of-function variants: 5 observed, 11.35 expected, observed/expected ratio (o/e) 0.44, 90% interval 0.23 to 0.93. The upper end of that interval is the gene's LOEUF score, 0.93, which puts it in group 3 of 6, group 1 being the genes least tolerant of losing a copy. Missense variants: 72 observed, 99.47 expected, observed/expected ratio (o/e) 0.72, 90% interval 0.6 to 0.88. Synonymous variants: 28 observed, 32.61 expected, observed/expected ratio (o/e) 0.86, 90% interval 0.63 to 1.18.
Homologues: Orthologues: chimpanzee ARL5A (100% identical), macaque ARL5A (100% identical), pig ARL5A (100% identical), rabbit ARL5A (100% identical), dog ARL5A (99% identical), rat Arl5a (99% identical), mouse Arl5a (99% identical), tropical clawed frog arl5a (93% identical), zebrafish arl5a (92% identical), guinea pig ARL5A (72% identical). Paralogues in human: ARL5B (80% identical), ARL5C (64% identical), ARF1 (49% identical), ARF3 (47% identical), ARL1 (47% identical), ARF4 (45% identical), ARF5 (44% identical), TRIM23 (44% identical), ARL2 (42% identical), ARF6 (41% identical), ARL3 (41% identical), ARL4C (37% identical), and 18 more.
Diseases named in the same sentence as ARL5A in open-access papers:
ARL5A is named in the same sentence as 10 diseases in open-access papers, as found by Europe PMC text mining. Sharing a sentence is not in itself a finding about the gene and the disease. The quoted sentences say what the papers report.
colorectal cancer (2 papers, 2020). A primary or metastatic malignant neoplasm that affects the colon or rectum. "ARL5A was found to be highly expressed in colorectal cancer and a target of miR-202-3P." (PMID 32426352, 2020). "Furthermore, the same study demonstrated that the downregulation of ARL5A and miR-202-3P expression leads to a similar reduction in colorectal cancer cell proliferation." (PMID 32426352, 2020).
melanoma (1 paper, 2021). A malignant, usually aggressive tumor composed of atypical, neoplastic melanocytes. "Investigating negative-regulated target genes, we found eight genes (ANKRD13C, ARL5A, ATL3, PAWR, PDCD6IP, SLC16A7, TFAM, UBP1) presenting a significant inverse correlation with miR-181a/b expression also in melanoma A375 sensitive cells." (PMID 33670365, 2021).
tumor (1 paper, 2022). "In contrast, the higher the expression of ARL5A and ARL11 genes, the lower the sensitivity to tumor-targeted drugs." (PMID 35774359, 2022).
ARL5A also shares sentences with these, for which no sentence is quoted: autism spectrum disorder (1 paper); diabetic retinopathy (1); epilepsy (1); Hypertension (1); Insulin resistance (1); Intellectual disability (1); sudden cardiac arrest (1).